INHBE (inhibin subunit beta E)
Description:
Inhibins and activins inhibit and activate, respectively, the secretion of follitropin by the pituitary gland. Inhibins/activins are involved in regulating a number of diverse functions such as hypothalamic and pituitary hormone secretion, gonadal hormone secretion, germ cell development and maturation, erythroid differentiation, insulin secretion, nerve cell survival, embryonic axial development or bone growth, depending on their subunit composition. Inhibins appear to oppose the functions of activins. Activin E is a homodimer of INHBE secreted by the liver that plays a crucial role in regulating metabolic homeostasis particularly in lipid metabolism and energy homeostasis. Plays a central role in the regulation of adipose tissue lipolysis by preventing the influx of fatty acids from adipose tissue into the liver. Mechanistically, signals via ACVR1C to activate SMAD2/3 signaling, suppressing PPARG target genes in adipose tissue, thereby reducing liver lipid content and improving glycemic control. Induces beige adipocyte formation and thermogenesis in response to cold exposure (By similarity).
Synonyms: activin; MGC4638
Tractability: Antibody: UniProt places it where antibodies can reach, with medium confidence; UniProt predicts a signal peptide or a membrane-spanning region; its Gene Ontology location is reachable by antibodies, with medium confidence. PROTAC: its protein half-life has been measured.
Gene: Protein-coding gene on chromosome 12 (57,452,323 to 57,459,280, forward strand). Ensembl gene ENSG00000139269.
Subcellular location: Secreted
Subcellular location (Human Protein Atlas): Vesicles; Predicted to be secreted
Pathways (Reactome):
Metabolism of proteins: Glycoprotein hormones
Gene Ontology:
Molecular function: cytokine activity; growth factor activity; hormone activity
Biological process: cell surface receptor protein serine/threonine kinase signaling pathway; negative regulation of adipose tissue development
Cellular component: extracellular matrix; extracellular region
Genetic constraint (gnomAD): Loss-of-function variants: 19 observed, 30.1 expected, observed/expected ratio (o/e) 0.63, 90% interval 0.44 to 0.93. The upper end of that interval is the gene's LOEUF score, 0.93, which puts it in group 3 of 6, group 1 being the genes least tolerant of losing a copy. Missense variants: 398 observed, 457.13 expected, observed/expected ratio (o/e) 0.87, 90% interval 0.8 to 0.95. Synonymous variants: 196 observed, 198.76 expected, observed/expected ratio (o/e) 0.99, 90% interval 0.88 to 1.11.
Homologues: Orthologues: chimpanzee INHBE (99% identical), pig INHBE (86% identical), rabbit INHBE (84% identical), mouse Inhbe (82% identical), macaque INHBE (81% identical), guinea pig INHBE (80% identical), rat Inhbe (80% identical), dog INHBE (78% identical). Paralogues in human: INHBC (40% identical), INHBA (34% identical), INHBB (33% identical), BMP6 (24% identical), BMP10 (24% identical), BMP8A (24% identical), BMP8B (24% identical), GDF11 (23% identical), BMP4 (23% identical), GDF7 (23% identical), TGFB3 (23% identical), BMP7 (22% identical), and 19 more.
Diseases named in the same sentence as INHBE in open-access papers:
INHBE is named in the same sentence as 31 diseases in open-access papers, as found by Europe PMC text mining. Sharing a sentence is not in itself a finding about the gene and the disease. The quoted sentences say what the papers report.
Insulin resistance (10 papers, 2018 to 2025). Increased resistance towards insulin, that is, diminished effectiveness of insulin in reducing blood glucose levels. "Recent studies have highlighted Inhibin βE (INHBE) as a novel putative hepatokine linked to insulin resistance and obesity." (PMID 40260391, 2025). "INHBE associates body mass index with insulin resistance, and knockdown INHBE with siRNA could inhibit body weight gain by diminished fat." (PMID 38665091, 2024). "In addition, a study reported the association between increased INHBE expression and insulin resistance and obesity in humans and mice, confirming that siRNA selectively silences the INHBE gene, thereby suppressing the increase in body weight and fat mass." (PMID 38344397, 2024). "As reduced levels of INHBE associate with a healthier fat distribution we asked whether, conversely, INHBE is upregulated in conditions of obesity and insulin resistance." (PMID 35896531, 2022). "Recent studies have shown that INHBE expression is induced by hepatic steatosis and insulin resistance, consistent with our finding of elevated EV-derived INHBE across all subgroups." (PMID 41354933, 2025). "INHBE gene expression in the liver correlates positively with insulin resistance and body mass index in humans, and its levels are elevated in db/db mice, a rodent model of type 2 diabetes." (PMID 40260391, 2025). "Two studies report a correlation between increased expression of INHBE and insulin resistance in both humans and mice." (PMID 35896531, 2022). "INHBE was identified as a novel putative hepatokine with hepatic gene expression that positively correlated with insulin resistance and body mass index in humans." (PMID 31636515, 2019). "Our study revealed that hepatic expression of INHBE mRNA is upregulated in humans with insulin resistance and obesity." (PMID 29596463, 2018). "Nevertheless, to our knowledge, this study is the first to report the metabolic significance of INHBE expression in human subjects with insulin resistance." (PMID 29596463, 2018). "Namely, analyses using liver biopsy samples from 15 subjects with varying degrees of insulin resistance indicated a positive correlation between hepatic INHBE mRNA and the HOMA-IR level." (PMID 29596463, 2018). "Inhibin βE (INHBE) was identified as a novel putative hepatokine with hepatic gene expression that positively correlated with insulin resistance and body mass index in humans." (PMID 29596463, 2018). "Knockdown of INHBE in these mice suppressed weight gain, reduced respiratory quotient and increased fat utilization, suggesting that INHBE may be an emerging player in metabolic regulation and a potential target for the treatment of insulin resistance." (PMID 40260391, 2025). "However, the association between insulin resistance and INHBE expression in the liver of humans has not been determined." (PMID 29596463, 2018). "Therefore, elevated INHBE expression in humans with insulin resistance may be caused by hepatic ER stress rather than hyperinsulinemia." (PMID 39948368, 2025). "Thus far, INHBE has been proposed as a hepatokine responsible for controlling energy homeostasis of white and brown adipose cells and is potentially associated with insulin resistance, but has not been studied in the developing human liver to our knowledge." (PMID 35255944, 2022). "However, the experimental data were not presented, and the role of the INHBE gene in insulin resistance and T2D was not discussed." (PMID 29596463, 2018).
Obesity (6 papers, 2018 to 2024). Accumulation of substantial excess body fat. "The association of INHBE pLOF variants with protection from diabetes had similar estimates in men and women or in obesity categories in an analysis corrected for potential collider effects." (PMID 35999217, 2022). "In addition, the subunit activin E, encoded by INHBE, can stimulate energy consumption by activating brown and beige adipocytes, suggesting that it may be a target for obesity prevention or treatment." (PMID 34616724, 2021). "Eighteen of those genes have reported associations with T2D and obesity in humans; of these genes there was most marked evidence for CLEC10A, MAPK8IP1, NEGR1, NQ01 and INHBE genes." (PMID 34391409, 2021). "Our preliminary in vivo siRNA study analyzing whole-body metabolic function suggest the possibility that the hepatokine INHBE decreases fat utilization and increases fat mass in the mice model of obesity." (PMID 29596463, 2018).
diabetes (4 papers, 2018 to 2025). "In human GWASs, predicted partial loss-of-function variants in INHBE are associated with reduced visceral white adipose tissue and improved metabolic parameters, including a lower incidence of diabetes and serum TG levels." (PMID 39948368, 2025). "Our studies in human subjects indicated that INHBE mRNA expression was upregulated under insulin-resistant and obese conditions in subjects with pre-diabetes." (PMID 29596463, 2018). "Further studies of rare LOF variants in INHBE did not reveal any associated adverse effects, suggesting that INHBE may be a promising new target for the treatment of lipid metabolism, diabetes, and cardiovascular disease." (PMID 38344397, 2024).
Hepatic steatosis (4 papers, 2022 to 2025). Steatosis is a term used to denote lipid accumulation within hepatocytes. "INHBE was significantly overexpressed in both hepatic steatosis and MASH compared to controls, and in MASH compared to steatosis, consistent with a potential role in disease progression." (PMID 41354933, 2025). "INHBE was consistently overexpressed across all three meta-analyses: hepatic steatosis vs. controls, MASH vs. controls, and MASH vs. steatosis." (PMID 41354933, 2025). "In participants with severe hepatic steatosis (n = 43), subgroup analysis showed increased COL18A1, AFM, PRG4, and INHBE and decreased C4A and APOA1." (PMID 41354933, 2025). "During the progression of normal liver to hepatic steatosis or NASH, there was a significant increase in INHBE expression." (PMID 39948368, 2025).
gastric cancer (3 papers, 2022 to 2023). A primary or metastatic malignant neoplasm involving the stomach. "INHBE expression is correlated with increased angiogenesis and the production of pro-inflammatory molecules in gastric cancer." (PMID 37999824, 2023). "INHBE (inhibin beta E subunit) is upregulated in gastric cancer and may contribute to immune dysfunction by suppressing T cell activity." (PMID 37999824, 2023).
nonalcoholic steatohepatitis (3 papers, 2022 to 2025). "We examined INHBE expression in the livers of obese monkeys with nonalcoholic steatohepatitis and in the livers of younger lean monkeys." (PMID 35896531, 2022).
type 2 diabetes (3 papers, 2018 to 2024). "Interestingly, variants of the ALK7 (ACVR1C) gene in humans leads to similar phenotypes (favorable fat distribution and protection from type 2 diabetes) as those shown in variants of the INHBE gene." (PMID 38533769, 2024).
breast carcinoma (2 papers, 2014 to 2024). "Hallmark Il6 Jak Stat3 Signaling (Overlap Genes: INHBE, REG1A): This signaling pathway is involved in inflammation and immune responses and has been linked to breast cancer progression and metastasis." (PMID 39000413, 2024).
hepatocellular carcinoma (2 papers, 2011 to 2018). A malignant tumor that arises from hepatocytes. "A previous report also indicated that treatment with insulin increased INHBE mRNA expression in the hepatoma cell line in vitro, which is consistent with the results of our study using primary hepatocytes." (PMID 29596463, 2018).
Hyperinsulinemia (2 papers, 2018 to 2025). An increased concentration of insulin in the blood. "Thus, hyperinsulinemia under insulin-resistant conditions in humans and animals may be one reason for the increased INHBE gene expression in the liver under pre-diabetic conditions." (PMID 29596463, 2018).
Abdominal obesity (1 paper, 2022). Excessive fat around the stomach and abdomen. "Our findings from exome-sequencing of over 360,000 individuals highlight INHBE as a novel therapeutic target to treat abdominal obesity and cardiometabolic disease." (PMID 35896531, 2022).
cervical carcinoma (1 paper, 2012). A carcinoma arising from either the exocervical squamous epithelium or the endocervical glandular epithelium. "INHBE is involved in regulation of human reproductive hormones and is dysregulated in endometrial and cervical carcinoma." (PMID 22590687, 2012).
liver cirrhosis (1 paper, 2022). "We did not observe an association with nonalcoholic liver disease or with liver cirrhosis outcomes, but the analysis was underpowered due to the rarity of INHBE pLOF alleles." (PMID 35999217, 2022).
malaria (1 paper, 2023). Malaria is a serious and sometimes fatal disease caused by a parasite that commonly infects a certain type of mosquito which feeds on humans. "The biological function of the 3 candidate biomarkers, ADAMTS18, ANGPTL4, and INHBE, has not been extensively characterized, and they have not been described before in the context of malaria." (PMID 37788095, 2023).
pancreatic cancer (1 paper, 2022). "INHBE is upregulated in pancreatic cancer, and it can predict the prognosis of patients with papillary renal cell carcinoma." (PMID 35627105, 2022).
renal cell carcinoma (1 paper, 2021). "The immune-related genes BIRC5, INHBE, and IL20RB were upregulated in a TMBhigh group and were associated with a poor prognosis, and a combination of PD-1 and CTLA-4 blockers was suggested for the treatment of advanced renal cell carcinoma with aberrations." (PMID 34795663, 2021).
steatosis (1 paper, 2025). Increased lipid within the cytoplasm of cells. "INHBE was the only protein consistently elevated across all three subgroups, whereas others showed subgroup-specific enrichment, such as immunoglobulins in Black women and complement or coagulation proteins in White participants and those with severe steatosis." (PMID 41354933, 2025). "Analysis of hepatic transcriptomic datasets demonstrated consistently higher INHBE expression across the MASLD spectrum, including metabolic dysfunction-associated steatohepatitis (MASH), while AFM expression was significantly higher in the MASH vs. steatosis comparison." (PMID 41354933, 2025).
virus infection (1 paper, 2019). "Although the TGFβ2 factor, recently recognized as a key factor in fibrosis induction, did not result upregulated by virus infection in HUVECs, other factors belonging to TGFβ superfamily were promoted in particular by HHV-6A, including GREM1 and INHBE, IL-4, IL-5, TNF, and MMP9." (PMID 31878218, 2019).
tumor (7 papers, 2017 to 2024). "More interestingly, INHBE was detected significantly increased while CD8 was decreased in mice tumor tissues." (PMID 32467669, 2020). "By proteomics approach, we observed that ECM components known to have tumor suppressor functions and anti-proliferative effects (i.e.: INHBE and PRG2) were found strongly downregulated in iCCA." (PMID 31687002, 2019). "To evaluate the clinical significance of inhibin beta family genes (INHBA, INHBB, INHBC, and INHBE) in STAD, we investigated their interrelations and compared their expression levels between tumor and normal tissues." (PMID 39543755, 2024). "Our results demonstrated that the mRNA expressions of IL-5, IL-1A, CXCL10, TNFSF4 and INHBE were significantly altered when regulating C1QTNF6, which suggested the essential implications of the cytokine-cytokine receptor interaction pathway in the process of C1QTNF6 regulating tumor progression." (PMID 35879698, 2022). "Because tumor nodules in C57 mouse abdominal cavity were small and adhered to surrounding connective tissue too tightly to separate, we injected ESRP1-ID8 and EV-ID8 cells subcutaneously in C57 mice to observe the changes of infiltrating CD8 + T cells and INHBE in tumor nodules." (PMID 32467669, 2020).
cancer (3 papers, 2021 to 2024). A tumor composed of atypical neoplastic, often pleomorphic cells that invade other tissues. "There is less data on INHBE and RNASE2 in malignancies, except for some bioinformatics studies reporting their predictive value in cancer prognosis, indicating that more in-depth studies on their biological functions are necessary in the future." (PMID 36812479, 2023). "Besides, the roles of seven genes (NR1D2, TANK, LRSAM1, PLXNA1, INHBE, HDGF, and ARAF) in SCLC have not been reported, however those genes have been reported to play a vital role in other type cancer." (PMID 34741430, 2021).
infection (2 papers, 2018 to 2022). The state of being infected such as from the introduction of a foreign agent such as serum, vaccine, antigenic substance or organism. "Among the genes under-expressed after 11 days post-infection, INHBE was found to be the most significantly down-regulated genes with 2.3-fold decrease in expression." (PMID 30024933, 2018). "Even more interestingly, the INHBE factor, which was not induced in the single-infected cells, was instead highly expressed at all time points (except at 0 d.p.i.)as a result of double infection, peaking at 7 d.p.i. with a 373.75-fold up-regulation compared with control cells." (PMID 36014018, 2022).
metabolic disease (2 papers, 2022 to 2025). A congenital disorder (due to inherited enzyme abnormality) or acquired (due to failure of a metabolically important organ) disorder resulting from an abnormal metabolic process. "We identified new associations with favorable adiposity and protection from metabolic disease for rare loss-of-function variants in INHBE, encoding a liver-produced circulating member of the TGF-β superfamily." (PMID 35999217, 2022). "Nevertheless, given the correlation between the partial loss of function of INHBE and reduced visceral adiposity risk of metabolic disease in human GWASs, a potential strategy could involve simultaneously activating both adipose lipolysis and fat burning in peripheral tissues." (PMID 39948368, 2025). "Hence, inhibition of INHBE may be a therapeutic approach for metabolic disease associated with improper fat storage." (PMID 35999217, 2022).
INHBE also shares sentences with these, for which no sentence is quoted: Acidosis (1 paper); anemia (1); cardiovascular disease (1); coronary heart disease (1); gout (1); Jaundice (1); ovarian carcinoma (1); papillary renal cell carcinoma (1); pulmonary fibrosis (1).